INS (insulin)
Diseases named in the same sentence as INS in open-access papers (continued):
Sharing a sentence is not in itself a finding about the gene and the disease.
Insulin resistance (continued). "Previous studies have indicated that long-term AdipoRon treatment (20 days) has negatively impacted whole-body insulin sensitivity, increasing Insulin Resistance (IR) through exacerbated adipose tissue lipolysis, increased hepatic gluconeogenesis, and an impaired muscle tricarboxylic acid cycle." (PMID 39859201, 2025). "Furthermore, according to a meta-analysis prebiotic treatment can enhance anthropometric and biochemical parameters such as body mass index (BMI), ALT, AST, fasting insulin, and insulin resistance in individuals with MASLD." (PMID 40893881, 2025). "Relevant animal studies suggest that electroacupuncture may alleviate insulin resistance in PCOS by modulating insulin signaling pathways." (PMID 40776915, 2025). "Moreover, diminished nitric oxide bioavailability due to endothelial injury compromises insulin‐mediated vasodilation, further aggravating insulin resistance." (PMID 41143273, 2025). "Furthermore, besides altered adipocytokine secretion, fat deposition and infiltration also contribute to insulin resistance by disrupting insulin signaling and glucose homeostasis." (PMID 40883486, 2025). "Elevated SF levels may further propagate the inflammatory response, leading to pancreatic β-cell dysfunction, heightened insulin resistance, and β-cell exhaustion, and may even contribute to hepatic insulin resistance and glucose dysregulation." (PMID 41210501, 2025). "The use of HI conditions stems from various studies indicating that elevated insulin levels could potentially play a role in fostering insulin resistance through dietary means, including HFD, and we check the levels of INSR in mouse primary hepatocytes." (PMID 39747658, 2025). "In addition to normalizing blood insulin levels, studies on diabetic rodents with insulin resistance have evidenced that quercetin treatment improves the action of this hormone." (PMID 40806520, 2025). "The presence of hyperglycemia and insulin resistance is known to promote fibrogenesis by inducing the expression of insulin and insulin-like growth factor 1 receptors and advanced glycation end products in hepatic stellate cells and upregulating TGFβ and connective tissue growth factor (CTGF)." (PMID 39861190, 2025). "IGF-1 is essential for optimal sensitivity to insulin, and deficient IGF-1 levels may lead to insulin resistance." (PMID 40141202, 2025). "Consequently, this insulin resistance and beta cell dysfunction often lead to substantially increased insulin requirements among insulin-treated patients." (PMID 39418352, 2025). "The anti-cytokine immunotherapy of type 2 diabetes is a new treatment method in recent years, especially blocking IL-1β in the process of impaired insulin secretion and insulin resistance, and can be used as a potential therapeutic target to reverse the quality and function of β cells." (PMID 40066372, 2025). "Experimental studies suggest that sustained high BP may impair vascular endothelial integrity and insulin signaling, thereby promoting insulin resistance." (PMID 41143273, 2025). "This study suggests that the Matsuda Index may be a valuable adjunct for identifying insulin in pediatric CF patients, with 22% of our cohort showing significant insulin resistance (Matsuda Index ≤ 4.5)." (PMID 41300682, 2025). "Further research is needed to determine whether RNF20 indirectly regulates systemic insulin homoeostasis through inter‐organ signalling mechanisms, providing potential new therapeutic targets for treating insulin resistance‐related metabolic disorders." (PMID 40522008, 2025). "In genetically predisposed individuals, chronic overproduction of interleukins, C-reactive protein, and tumor necrosis factor-α may impair β-cell insulin secretion and contribute to insulin resistance." (PMID 41357171, 2025).
Insulin resistance (continued). "Based on the results of insulin and glucose concentrations, the Homeostatic Model Assessment for Insulin Resistance (HOMA-IR) index was calculated according to the formula: fasting plasma insulin concentration (mU/L) × fasting plasma glucose concentration (mM)/22.5)." (PMID 41028841, 2025). "Fasting plasma glucose and insulin levels significantly decreased, accompanied by improvements in the homeostatic model assessment for insulin resistance (HOMA-IR) index, glycosylated hemoglobin (HbA1c), triglyceride-to-glucose ratio, and the triglyceride-glucose (TyG) indexes (all p < 0.001)." (PMID 41010457, 2025). "Impaired glucose uptake into the tissue could be attributed to decreased insulin secretion or the onset of insulin resistance." (PMID 39861408, 2025). "In fact, it was shown that the pro-inflammatory cytokines IL-6, MCP-1, IL-1β, and TNF-α secreted by hypertrophic adipose tissue in obese individuals can disrupt insulin signalling and promote insulin resistance, contributing to the pathophysiology of diabesity." (PMID 41155431, 2025). "T2D is due to a progressive non-autoimmune loss of adequate β-cell insulin secretion, frequently with a background of insulin resistance and metabolic syndrome." (PMID 41011279, 2025). "According to their findings, these patients benefited greatly from resveratrol supplementation in conjunction with conventional antidiabetic treatment, including significant decreases in blood glucose, HbA1c, and insulin levels, mitigating insulin resistance, and HDL cholesterol levels." (PMID 39861406, 2025). "High parity, accompanied by high estrogen exposure, may result in long cumulative exposure to insulin resistance, because insulin sensitivity decreases during pregnancy and high estrogen levels." (PMID 39663299, 2025). "In the pancreas, local neurogenic inflammation, mediated by TRPV1-expressing sensory neurons, may impair β-cell function, reduce insulin secretion, and promote insulin resistance." (PMID 40964166, 2025). "Iatrogenic peripheral hyperinsulinemia, resulting from peripheral insulin administration in type 1 diabetes, may increase insulin resistance and impair endothelial function." (PMID 40045281, 2025). "Insulin resistance is an increasingly prevalent pathological condition in which the body’s cells (predominantly skeletal muscle, adipose tissue, and hepatocytes) fail to respond appropriately to insulin." (PMID 40807271, 2025). "However, it is challenging to define the sequential relationship between insulin sensitivity and insulin secretion, as they are tightly interlinked, and evidence suggests that hyperinsulinemia can alternatively precede insulin resistance." (PMID 40013621, 2025). "However, previous data demonstrating that chemerin impairs insulin signaling by acting on several proteins of its cascade suggest that upregulated chemerin is the determinant of hyperinsulinemia and insulin resistance." (PMID 41007694, 2025). "However, insulin levels and the homeostatic model assessment of insulin resistance (HOMA-IR) were significantly higher in the PCOS group." (PMID 40155948, 2025). "These cytokines not only have the potential to directly damage pancreatic β-cell function but may also worsen insulin resistance by interfering with insulin signaling pathways." (PMID 40137495, 2025). "However, prolonged nutrient surplus eventually results in the dysregulation of insulin signaling, commonly known as “insulin resistance”." (PMID 40868889, 2025). "The condition is classified into several types, with type 1 diabetes resulting from autoimmune destruction of pancreatic beta cells, leading to insulin deficiency, and type 2 diabetes stemming from a combination of insulin resistance and inadequate insulin secretion." (PMID 39835172, 2025).
Insulin resistance (continued). "Its primary pharmacodynamic action is believed to involve activation of the AMP-activated protein kinase (AMPK) pathway, which enhances insulin sensitivity and improves peripheral insulin resistance in patients with T2DM—an axis potentially critical to maintaining cerebral glucose homeostasis." (PMID 40648562, 2025). "Reduced blood pressures, fasting serum glucose, insulin levels, insulin resistance, Serum tumor necrosis factor α, C-reactive protein, the total and low-density lipoprotein cholesterol, and triglycerides; increased total antioxidant status and high-density lipoprotein cholesterol." (PMID 39857788, 2025). "Several investigations have indicated a notable decrease in serum lipid profiles, fasting glucose levels, insulin resistance, insulin, HbA1c, interleukin‐6, TNF‐α, CRP, and liver enzymes aspartate aminotransferase, alanine transaminase after consumption of propolis and increase HDL‐C." (PMID 41245948, 2025). "Therefore, the treatment of insulin resistance should be based on insulin signaling, lipid metabolism, glucose metabolism, oxidative stress, and inflammation." (PMID 40881124, 2025). "Furthermore, previous research has shown that ExSn can improve insulin sensitivity and reduce insulin resistance, which helps regulate lipid metabolism." (PMID 40814152, 2025). "Polysaccharides may bind cholesterol and free fatty acids in the gastrointestinal tract, thereby reducing lipid absorption and blood lipid formation, while to some extent improving insulin sensitivity and thus alleviating insulin resistance." (PMID 41050449, 2025). "Beginning in the third week, the combined administration of Yupingfeng and metformin significantly reduced fasting insulin levels, blood glucose concentrations, and insulin resistance compared to the control group, with further marked reductions observed by the seventh week (p< 0.01)." (PMID 40771277, 2025). "Increased autophagy in the heart is correlated with the production of ROS, which contributes to insulin resistance but may also function as an endogenous self-protective mechanism downstream of the PI3K/AKT insulin signaling pathway." (PMID 40369521, 2025). "Additionally, obesity-induced insulin resistance disrupts insulin/IGF-1 signaling, thereby overactivating the PI3K/Akt/mTOR pathway." (PMID 41048699, 2025). "However, most animal studies have been conducted using indices centered on insulin resistance and insulin secretion ability." (PMID 41433229, 2025). "Both TN and UL have been associated with insulin resistance, although the relationship between HMG and INS remains unclear." (PMID 40927293, 2025). "The link between persistently high AIP and increased T2DM risk may be explained by a “vicious cycle,” in which dyslipidemia leads to insulin resistance and elevated insulin levels." (PMID 39920728, 2025). "This impairment in insulin signaling can lead to insulin resistance and impaired glucose tolerance." (PMID 39860000, 2025). "Hyperglycaemia is known to increase oxidative stress and generation of ROS, which may propagate the development of further insulin resistance, reduce insulin production, and mediate sequalae of hyperglycaemia." (PMID 41226805, 2025). "Prolonged administration of insulin causes a decreased response of insulin in diabetic patients independent of high glucose suggesting that hyperinsulinemia is self‐sufficient to induce insulin resistance." (PMID 39471069, 2025). "These inflammatory mediators disrupt insulin signaling pathways, leading to insulin resistance." (PMID 40703156, 2025). "Consequently, in our patient cohort, the prevalence of IGT and of type 2 diabetes as well as fasting serum blood glucose, HbA1c%, insulin level and insulin resistance characterizing HOMA-IR were significantly higher compared to the control group." (PMID 40463745, 2025).
Insulin resistance (continued). "Its mechanism may involve reducing FBG levels, improving glucose tolerance, increasing insulin sensitivity, and enhancing insulin resistance in diabetic mice by boosting antioxidant effects and repairing pancreatic islet cells." (PMID 40336535, 2025). "In addition to the presence of insulin resistance (i.e., impaired glucose tolerance, impaired fasting glucose, type II diabetes mellitus, or lowered insulin sensitivity), there must be two or more of any other metabolic risk factors for the diagnosis of MetS." (PMID 40217852, 2025). "Fasting insulin is considered the most practical approach in assessing insulin resistance." (PMID 40884153, 2025). "Furthermore,compound 1 was able to reactivate an important kinase,protein kinase B (Akt), in the insulin signaling pathway in HepG2cells with high-glucose-induced insulin resistance." (PMID 40392982, 2025). "Of these three most-detected phthalate metabolites in our study, MiBP showed a significant positive correlation with key indicators of obesity and metabolic syndrome, including fat mass (p = 0.012), fasting insulin (p = 0.002), and insulin resistance (HOMA-IR; p = 0.0004)." (PMID 41154898, 2025). "Different subtypes of type 2 diabetes have been proposed, including an insulin resistance phenotype with less severe beta cell dysfunction; and a relatively low BMI/insulin sensitive subtype with more marked beta cell insufficiency and earlier progression to exogenous insulin therapy." (PMID 40991018, 2025). "However, insulin levels as well as insulin resistance as measured with the HOMA-IR were higher in participants with depression (t = −2.4, p = .020)." (PMID 39905823, 2025). "ASOs modulating IRS1 expression may be possible to restore proper insulin signaling and reduce insulin resistance, improving the metabolic state of the patient." (PMID 39944202, 2025). "Insulin also reduces circulating ApN levels, suggesting that hyperinsulinemia, observed in cases of insulin resistance, could contribute to lower plasma adiponectin." (PMID 40075777, 2025). "FGF1 is another secreted protein that has been shown to dampen hepatic glucose output by suppressing adipose lipolysis, improve systemic insulin sensitivity by reducing adipose inflammation, and alleviate hepatic steatosis, inflammation, and insulin resistance." (PMID 37961647, 2025). "For instance, elevated circulating levels of fatty acid-binding protein 4 (FABP4) and glutathione peroxidase 3 (GPX3) were associated with declining insulin secretion, independent of insulin resistance." (PMID 40768044, 2025). "GKB extract increases pancreatic β-cell function and improves insulin sensitivity by enhancing IRS-2 transcription, as IRS-2 is a crucial element in insulin signaling, and studies have found that a deficiency of IRS-2 causes insulin resistance." (PMID 40150513, 2025). "It is therefore hypothesized that the downregulation of insulin synthesis in the fat body by Toll signaling may induce a slowdown in overall insect growth through a mechanism similar to mammalian insulin resistance." (PMID 39859663, 2025). "Therefore, the present comprehensive meta-analysis was conducted to evaluate the effect of fenugreek seed on glycemic parameters including FBG, 2hPPG, HbA1c, as well as Insulin and Insulin resistance (HOMA-IR)." (PMID 41509111, 2025). "Although further research is needed, dysregulation of phosphate homeostasis may impair insulin signaling, thereby triggering insulin resistance and decreasing cellular utilization of glucose." (PMID 40701574, 2025). "Some report Alzheimer's-like glucose hypometabolism with increasing peripheral insulin resistance in type 2 diabetes and prediabetes, while others find peripheral insulin resistance to be the strongest predictor for enhanced BGM during insulin stimulation from hyperinsulinemic clamps." (PMID 39185744, 2025).
Insulin resistance (continued). "Moreover, TNF-α has been identified as a crucial factor in disrupting the insulin signaling system and promoting insulin resistance." (PMID 40541990, 2025). "The insulin resistance hypothesis centres on the observation that AD brains exhibit impaired insulin signalling and glucose hypometabolism, features akin to peripheral insulin resistance seen in type 2 diabetes mellitus (T2DM)." (PMID 40942007, 2025). "The Metabolic Score for Insulin Resistance (METS-IR), introduced in 2018, is a novel index designed to assess cardiometabolic risk in both healthy and at-risk individuals, making it a promising tool for screening insulin sensitivity." (PMID 40218212, 2025). "T2DM is characterized by pancreatic β-cell dysfunction and insulin resistance, and is recognized as a multisystem metabolic disorder involving pathways such as the gut-brain axis, insulin/peripheral resistance, etc strongly correlated with obesity and cardiovascular diseases." (PMID 41561058, 2025). "Type I diabetes is characterized by a chronic autoimmune destruction of pancreatic beta cells and a decrease in insulin production, while type II diabetes is characterized by insulin resistance and a progressive decline in the capacity of beta cells to produce insulin." (PMID 41030912, 2025). "Additionally, to evaluate the beneficial effect of Avn-C on HFD-induced hippocampal insulin resistance, the hippocampal insulin levels were quantified using an ELISA assay." (PMID 40871707, 2025). "Evaluation results of intraperitoneal glucose tolerance test (GTT) and the insulin tolerance test (ITT) showed that microneedles under near-infrared irradiation could significantly alleviate HFD-induced insulin resistance." (PMID 40903781, 2025). "Changes in endothelial permeability and decreased peripheral blood flow due to HTN may limit insulin delivery and promote insulin resistance, which impairs glucose uptake." (PMID 40218093, 2025). "Mice on a high-fat diet (HFD) typically exhibit characteristics of type 2 diabetes, including increased weight and fat, elevated fasting glucose and insulin levels, impaired glucose tolerance, and pronounced insulin resistance compared to mice on a low-fat diet." (PMID 40726918, 2025). "Excess FFAs act on insulin downstream signaling pathways in muscle tissue, liver, and pancreas, leading to sustained high plasma glucose levels and hyperinsulinemia, thereby inducing insulin resistance." (PMID 40862144, 2025). "MetS is characterized by insulin resistance, which leads to abnormal insulin sensitivity." (PMID 39815341, 2025). "Furthermore, using pharmacological phosphatase inhibitors, we demonstrated the involvement of lEV-carried PTP1B and sEV-carried PP2A from insulin-resistant individuals in the development of insulin resistance." (PMID 39422717, 2025). "Insulin resistance appears in the early stage, followed by a defect in insulin secretion, leading to severe hyperglycemia, which might be too severe for the treatment of exercise alone to reduce blood glucose levels." (PMID 41030325, 2025). "Insulin resistance is a critical health issue in which the cells become less responsive to insulin." (PMID 40076938, 2025). "In terms of data analysis, it may have been beneficial to include other blood biomarkers of insulin resistance, such as fasting insulin, C-peptide, and fructosamine, to further assess and confirm the impact of the intervention." (PMID 40289997, 2025). "Numerous animal studies revealed that yacon and its extracts improve beta cell function, insulin resistance, plasma insulin, and glucose levels, while reducing TG and very low‐density lipoprotein (VLDL) in diabetic rats and lowering postprandial serum TG in normal rats." (PMID 41152200, 2025). "In addition to increasing NO availability, nitrate increases plasma insulin, decreases hyperglycemia, and improves insulin resistance, as demonstrated in animal models of T2D." (PMID 40575264, 2025).